TNF (tumor necrosis factor)
Diseases named in the same sentence as TNF in open-access papers (continued):
Sharing a sentence is not in itself a finding about the gene and the disease.
Crohn disease (continued). "Combining MTX with anti-TNF therapy appears to be an effective and safe treatment for patients with Crohn’s disease, particularly those with severe disease who are less responsive to monotherapy." (PMID 39807419, 2024). "Most clinical research on IFX has focused on Crohn's disease, which is characterized as a Th1-type condition driven by pro-inflammatory cytokines like TNF-α." (PMID 39221404, 2024). "The RED extract showed an optimal safety profile, and a significant reduction in TNF-α and other pro-inflammatory cytokines/chemokines, suggesting its potential use as adjuvant therapy to reduce symptoms and prevent relapses in Crohn’s disease patients." (PMID 38999902, 2024). "Reaching a diagnosis of a cutaneous eruption in a Crohn's disease (CD) patient treated with anti-tumor necrosis factor alpha (anti-TNFα) can be challenging." (PMID 38681333, 2024). "The Personalised Anti-TNF Therapy in Crohn’s Disease [PANTS] study is a UK-wide prospective observational cohort study of anti-TNF therapy outcome in anti-TNF-naive Crohn’s disease patients [ClinicalTrials.gov identifier: NCT03088449]." (PMID 37776235, 2024). "It affected the larynx of a 73 y.o. man who was an active hunter and was receiving a tumor necrosis factor inhibitor for Crohn’s disease." (PMID 39057757, 2024). "In this prospective observational study, fifty-four patients diagnosed with active Crohn’s disease and undergoing anti-TNF-α biological therapy were enrolled and subjected to nutrient intake analysis through a daily food diary." (PMID 38257172, 2024). "A total of 148 patients were included with an overall 48.9% of complex behavior of the Crohn’s disease and 97.2% of previous anti-TNF exposure." (PMID 38942890, 2024). "TNF-α inhibitors, such as infliximab, adalimumab, certolizumab pegol, and golimumab, are increasingly being used in the treatment of Crohn’s Disease (CD) and Ulcerative Colitis (UC)." (PMID 39768250, 2024). "A strong correlation in pathophysiology related to IL-1 and IL-6 and TNF has been established between the two conditions and supplementation of anti-TNF therapy in Crohn's disease patients has resulted in the resolution of HS symptoms." (PMID 39529755, 2024). "The regimen proved effective, as it favorably influenced the outcome of Crohn’s disease compared to the effects evident in the population receiving TNFα inhibitors." (PMID 39199994, 2024). "Recently, Ruminococcus gnavus species has been shown to produce and secrete a complex glucorhamnan polysaccharide that induces inflammation in Crohn's disease by contributing to TNF‐α release." (PMID 39620016, 2024). "In our series (Table A1), other observed risk factors were juvenile rheumatoid arthritis under immunosuppressive treatment (methotrexate, prednisone, and an interleukin-6 receptor blocker) and Crohn’s disease (on a tumor necrosis factor-alpha blocker)." (PMID 38920894, 2024). "As TNF-α antagonists are an effective treatment for Crohn disease, some studies have shown some success in treating patients with MIS-C and Crohn disease at the same time." (PMID 38510081, 2024). "After the first use of infliximab in Crohn’s Disease (CD) in 1995, the wide-scale introduction of anti-tumour necrosis factor alpha (anti-TNF alpha) medications revolutionised the treatment of inflammatory bowel diseases (IBDs)." (PMID 39458960, 2024). "Biologic therapy, specifically anti-TNF therapy, has been the mainstay of management of Crohn's disease for many years." (PMID 38388611, 2024). "We describe a therapeutic atlas for Crohn’s disease (CD) and ulcerative colitis (UC) following adalimumab, an anti-tumour necrosis factor (anti-TNF) treatment." (PMID 39438660, 2024). "In this study, we analyzed the shared processes of pyroptosis in Ulcerative colitis (UC) and Crohn's disease (CD), as well as explored the correlation between the burden of pyroptosis and the results of anti-TNF treatment based on bioinformatics analyses." (PMID 37740137, 2023).
Crohn disease (continued). "Several monoclonal antibodies have been approved for the treatment of Crohn's disease, such as anti-TNF agents and anti-integrin agents." (PMID 37016327, 2023). "Anti-tumor necrosis factor (TNF) agents are the mainstay of therapy for moderate-to-severe Crohn's disease (CD)." (PMID 37554999, 2023). "Anti-tumor necrosis factor agents (anti-TNFs) have become one of the primary medical therapies for Crohn’s disease (CD)." (PMID 39132048, 2023). "Patients aged 18 to 80 years, diagnosed with moderate-to-severe Crohn’s disease (CD) at least three months prior and having an inadequate response or intolerance to corticosteroids, immunosuppressants and/or anti-TNF, were selected for the trial." (PMID 38004446, 2023). "In a retrospective Canadian study, earlier initiation of anti-TNF-α treatment in patients with Crohn’s disease and ulcerative colitis was more common in adolescents and was associated with higher PCDAI/PUCAI and lower serum albumin levels at diagnosis." (PMID 37189883, 2023). "Anti-TNFα agents, including Adalimumab, Infliximab, Certolizumab, and Golimumab are now used as biological gold-standard therapy for both colitis ulcerosa and Crohn's disease management." (PMID 37838173, 2023). "Ruminococcus species can suppress TNF-α, and its abundance is lower in patients with Crohn’s disease than in healthy individuals." (PMID 37328529, 2023). "In Crohn’s disease (CD), the combination of anti-tumor necrosis factor-alpha (TNF-α) agents and immunomodulators (IMMs) such as methotrexate (MTX) and azathioprine (AZA) is known to increase instances of complete remission and to prevent recurrence." (PMID 37761016, 2023). "Shared similarities in the ethiopathogenesis of periodontitis and Crohn’s disease include defective neutrophil chemotaxis, impaired TNF-α expression, and atypical Th1 cell response." (PMID 36768711, 2023). "The use of anti-TNF therapy was lower for both Crohn’s disease and ulcerative colitis, compared with younger people with IBD." (PMID 37674503, 2023). "We report an intriguing case study, featuring a 23-year-old male patient with Crohn's Disease who had been receiving a combination therapy of thiopurine and anti-TNF for 6 years and was diagnosed with primary hepatic diffuse large B-cell lymphoma." (PMID 37753362, 2023). "In various inflammatory disorders, including Crohn's disease (CD), TNF-alpha is known to play a crucial role in intestinal inflammation and induce increase in the permeability of intestinal epithelial tight junctions (TJ)." (PMID 38008714, 2023). "Tissue resident CD4+ T cells are expanded in the mucosa of Crohn's disease patients and more avidly produce IL-17A and TNFα relative to controls." (PMID 37456566, 2023). "Treatment involves steroids for mild‐moderate Crohn's disease and immunosuppressants and biologics (e.g., anti‐TNFα antibodies, anti‐integrin antibodies, IL‐23/‐12 antagonists) for moderate to severe disease." (PMID 37983917, 2023). "TNF mAbs were translated into e.g. Remicade® and Humira® for the treatment of Crohn’s disease and Ulcerative Colitis in addition to the pathologies treated by Enbrel®." (PMID 36875111, 2023). "Twenty-nine patients (15 with Crohn’s disease [CD], 14 with ulcerative colitis [UC]) underwent colonoscopy with pCLE before and 12 to 14 weeks after starting anti-TNF or anti-integrin α4β7 therapy." (PMID 36378498, 2023). "In Crohn’s disease, early and effective use of TNF-α blockers also prevented the development of disease complications, for example, strictures or penetrating ulcerations and disease progression." (PMID 37189883, 2023). "Therapy with anti-tumor necrosis factor (TNF) has dramatically changed the natural history of Crohn’s disease (CD)." (PMID 37240037, 2023). "One VEO-CD patient underwent a subtotal colectomy 9 months after diagnosis because of a severe refractory Crohn's disease, resistant to anti-TNFα therapy." (PMID 37082701, 2023).
Crohn disease (continued). "25-Hydroxyvitamin D concentrations were measured in stored baseline samples from 659 infliximab- and 448 adalimumab-treated patients in the Personalised Anti-TNF Therapy in Crohn’s disease (PANTS) study." (PMID 37265586, 2023). "The anti-TNF strategy also restored the microbiota composition of patients with Crohn’s disease to a healthy state." (PMID 37759722, 2023). "Inflammatory markers such as C-reactive protein (CRP) and white blood cell count decreased in children and adolescents with moderate-to-severe Crohn’s disease on TNF-α inhibitor therapy." (PMID 37189883, 2023). "These genes include those targeted by Crohn's disease therapies, such as TNFα, integrin adhesion molecule α4β7, IL‐23/‐12, and genes that belong in their signaling pathways." (PMID 37983917, 2023). "Infliximab is a monoclonal antibody that binds and neutralises tumour necrosis factor‐alpha (TNF‐α), which is present in high levels in the blood serum, mucosa and stool of people with Crohn's disease." (PMID 37982428, 2023). "Anti-tumor necrosis factor inhibitors are increasingly being recommended to treat and control a wide range of diseases, including Crohn's disease, ulcerative colitis, rheumatoid, and psoriatic arthritis." (PMID 37485130, 2023). "Anti-tumor necrosis factor (TNF) therapy is used to induce and maintain remission in Crohn’s disease (CD) patients." (PMID 37658984, 2023). "For IBD therapy, monoclonal antibodies against tumor necrosis factor such as infliximab, adalimumab, certolizumab pegol and golimumab have all been approved worldwide for the treatment of moderate-to-severe active Crohn’s disease and/or ulcerative colitis." (PMID 36937844, 2023). "Early anti-TNF therapy is known to play a pivotal role in improving the long-term outcomes of Crohn’s disease." (PMID 36824176, 2023). "The downregulation of TNF-α can significantly downregulate the inflammation of Crohn’s disease, and the content is positively correlated with inflammation." (PMID 36902386, 2023). "Anti-TNF therapy has been found to exert an influence on long-term nutritional status and even reverse malnutrition in patients with Crohn’s disease." (PMID 36824176, 2023). "Few real-world studies compared anti-TNFs with vedolizumab or ustekinumab in biologic-naïve patients with CD, given these new biologic therapies are generally used in treating patients with anti-TNF refractory Crohn’s disease." (PMID 35453498, 2022). "For example, tmTNF expression in the gut is predictive for anti-TNF treatment response in Crohn’s disease." (PMID 35216345, 2022). "Four of these had Crohn ́s disease and six had prior surgery for UC; another two cases had previously received treatment with TNFα-inhibitors as an exclusion criterion." (PMID 35173908, 2022). "For example, the anti-tumor necrosis factor (TNF) drug infliximab is effective for treating Crohn’s disease with a good safety profile." (PMID 36685554, 2022). "L. reuteri 6475 can inhibit TNF-α, a pro-inflammatory cytokine, in monocyte-derived macrophages isolated from children with Crohn’s disease, as well as toll-like receptor (TLR) 2 and TLR4-activated human and murinemonocytoid cell lines." (PMID 35966270, 2022). "For ulcerative colitis and Crohn’s disease, the occurrence of adverse events per year of follow-up was similar between vedolizumab and anti-TNF (p = 0.274 and p = 0.876, respectively)." (PMID 36498541, 2022). "A total of 234 patients with Crohn’s disease (CD) who received their first anti-TNF therapy were enrolled." (PMID 35743732, 2022). "No study has performed a face-to-face comparison of biologics after the failure of the first anti-TNF agent in patients with Crohn’s disease (CD)." (PMID 36457080, 2022). "A clinical pilot study showed that consumption of anthocyanins from purple corn reduced plasma levels of inflammatory markers and improved the response to Infliximab, a chimeric monoclonal antibody against TNF-α, in Crohn’s Disease patients." (PMID 35453479, 2022).
Crohn disease (continued). "Antitumor necrosis factor (anti-TNF) agents are effective therapies in managing patients with Crohn’s disease." (PMID 36185868, 2022). "The 2010 ECCO guideline on the management of Crohn’s disease stated that patients who have poor clinical prognostic factors are most suitable for early thiopurine, methotrexate and or anti-TNF therapy." (PMID 35368318, 2022). "Stool samples were collected from a cohort of patients with an established diagnosis of IBD, either ulcerative colitis or Crohn’s disease, following completion of the induction phase of anti-TNF therapy." (PMID 34761733, 2022). "Previously, we demonstrated that IELs from patients with either axSpA or Crohn’s disease are enriched for TNF production compared to controls." (PMID 36159826, 2022). "Strikingly, Erysipelotrichaceae has been demonstrated to mediate the TNF-alpha-mediated Crohn’s disease." (PMID 36211488, 2022). "This study was unique in that it not only reported an accurate measurement of tissue levels of anti-TNF drug in luminal Crohn’s disease, but also found that these levels correlated well with the serum drug levels." (PMID 35407421, 2022). "Current practical guidelines recommend anti-TNF as the first-line biological therapy in biologic-naïve patients with moderately to severely active luminal Crohn’s disease or ulcerative colitis." (PMID 35453498, 2022). "A genome-wide significant association between the CD96 locus and the production of antibodies to anti-TNF treatment was found in Crohn's disease (CD)." (PMID 35769669, 2022). "In a small sample, adverse events related to TNF-α therapy occurred in 32% of pediatric patients with Crohn’s disease." (PMID 36304532, 2022). "Our objective was to investigate the safety and effectiveness of anti-TNF in NPC1 patients with Crohn’s disease." (PMID 35694196, 2022). "A 28-year-old Caucasian male was regularly followed-up for a Crohn’s disease (CD) treated by infliximab, an anti-tumor necrosis factor (TNF) therapy." (PMID 35768794, 2022). "A recent cohort recruiting 225,090 individuals with Crohn’s disease and 188,420 with ulcerative colitis showed that patients treated with anti-TNF agents were less likely to develop colorectal cancer." (PMID 36618924, 2022). "Patient 2 initially had severe Crohn’s disease with a wPCDAI of 82.5 and showed a significant improvement in score to 17.5 over the first 90 days of treatment with anti-TNF therapy." (PMID 35694196, 2022). "Vedolizumab therapy was initiated in the patients due to anti-tumor necrosis factor resistance (17 ulcerative colitis and 26 Crohn’s disease) or anti-tumor necrosis factor side effects (1 ulcerative colitis and 4 Crohn’s disease)." (PMID 35946879, 2022). "Anti-TNF biologics have been shown to markedly improve the quality of life for patients with Crohn’s disease (CD), yet one-third of patients fail to benefit from this treatment." (PMID 36232469, 2022). "We have previously published results showing that normalization (< 10 000 copies/μg mRNA) of mucosal TNF mRNA when discontinuing anti-TNF treatment in both UC and Crohn ́s disease prolonged the time in remission." (PMID 36384477, 2022). "This study clarifies the long-term effectiveness of ustekinumab (UST) in antitumor necrosis factor (anti-TNF) refractory Crohn’s disease in Middle Eastern patients." (PMID 36185868, 2022). "Around 13% of patients with Crohn’s disease had very high disease activity upon diagnosis and received an anti-TNF-α blocker as a first-line treatment." (PMID 36304532, 2022). "Some studies have also demonstrated the overexpression of intestinal TNF-α in patients with Crohn’s disease, and anti-TNF-α antibody treatment has been used to treat patients with IBD." (PMID 35756539, 2022). "Vedolizumab therapy was initiated in the patients due to anti-TNF resistance (17 UC and 26 Crohn’s disease) or anti-TNF side effects (1 UC and 4 Crohn’s disease)." (PMID 35946879, 2022).
Crohn disease (continued). "Inhibition of the TNF alpha pathway, group 12/23 cytokines, and lymphocyte migration is used in the treatment of severe or moderate ulcerative colitis and Crohn’s disease." (PMID 35207271, 2022). "Ustekinumab plus vedolizumab and vedolizumab plus anti-TNF were the most used CoTs for Crohn’s disease." (PMID 35207347, 2022). "The first patient reported to have listeria infection complicating targeted therapy was a patient with Crohn's disease on infliximab, an anti-TNFα monoclonal antibody." (PMID 35572995, 2022). "g__Ruminococcus_gnavus_group can produce an inflammatory polysaccharide, which can induce dendritic cells to produce inflammatory cytokines such as TNF-α, further leading to the progression of Crohn’s disease." (PMID 36238574, 2022). "The opposite direction of the expression of MACF1 transcript between non-responders relative to responders in healthy and inflamed colon tissue additionally suggests an important role of this gene in anti-TNF response in Crohn’s disease." (PMID 36145641, 2022). "Patient 3 was a 17-year-old female with Crohn’s disease under adalimumab therapy, a disease-modifying monoclonal antibody inactivating tumor necrosis factor-alpha." (PMID 35337010, 2022). "We identified 4 patients with NPC1 and Crohn’s disease-like intestinal inflammation who received anti-TNF therapy." (PMID 35694196, 2022). "In a multicenter randomized prospective trial that investigated moderate to severe Crohn’s disease, a significantly greater proportion of patients treated with a first-line anti-TNF-α therapy achieved clinical and endoscopic remission." (PMID 36304532, 2022). "The pathogenesis of Crohn’s disease is mainly related to the inflammatory response dominated by cytokines IL-1, IL-6, IL-8, TNF-α and IFN-γ secreted by Th1 and Th17 cells." (PMID 35979355, 2022). "Moreover, the gut bacterium Ruminococcus gnavus synthesizes and secretes an inflammatory polysaccharide that induces the production of inflammatory cytokines like TNFα by dendritic cells and may contribute to the association between R. gnavus and Crohn’s disease." (PMID 36144422, 2022). "Treatment with oral corticosteroid and then tumor necrosis factor-α blockers (adalimumab and infliximab) led to remission of Crohn’s disease." (PMID 35538558, 2022). "In paediatric and adult patients with Crohn’s disease anti-TNF agents (such as infliximab and adalimumab) are standard of care to induce and maintain remission." (PMID 35694196, 2022). "We identified 4 NPC1 patients with Crohn’s disease (CD)-like intestinal inflammation treated using anti-TNF therapy (mean age of onset 8.1 years, mean treatment length 27.75 months, overall treatment period 9.25 patient years)." (PMID 35694196, 2022). "The multivariate analysis in the PANTS (Personalising Anti-TNF Therapy in Crohn’s Disease) study demonstrated that low drug concentration at Week 14, for both IFX and ADA, predicted immunogenicity." (PMID 36196255, 2022). "The EXPLORE study evaluated the incidence and indicators of suboptimal responses to first-line anti-tumor necrosis factor (TNF) in patients with ulcerative colitis (UC) or Crohn’s disease (CD)." (PMID 35120446, 2022). "A meta-analysis also confirmed the efficacy of anti-TNF-α biologics for inducing and maintaining mucosal healing in patients with Crohn’s disease and ulcerative colitis." (PMID 35887724, 2022). "Through the action of the TNF signaling pathway, anti-TNF therapy was approved for Crohn’s disease in 1998 and has transformed the treatment landscape, allowing for improved patient response and remission rates." (PMID 36118873, 2022). "Many clinical trials, including ACCENT I (A Crohn’s Disease Clinical Trial Evaluating Infliximab In a New Long-term Treatment Regimen), have assessed the safety and efficacy of anti-TNF-alpha antibodies in the treatment of IBD." (PMID 35207271, 2022).